PIK3CA (phosphatidylinositol-4,5-bisphosphate 3-kinase catalytic subunit alpha)
Diseases named in the same sentence as PIK3CA in open-access papers (continued):
Sharing a sentence is not in itself a finding about the gene and the disease.
tumor (continued). "In contrast, PIK3CA mutations in codon 1047 (kinase domain) were more common in ER− tumours (83 out of 162 ER− versus 382 out of 942 ER+ P=0.01243,)." (PMID 27161491, 2016). "PCR-based sequencing for hot spot mutations of KRAS, BRAF and PIK3CA genes in CTCs revealed similar mutations as tumor biopsies for 77.8% of the patient samples." (PMID 27863403, 2016). "In the PIK3CA mutated TNBC PDX model (HBCx-4B) a significant reduction in tumor volume (RTV) was observed in mice receiving celecoxib as compared to control mice from day 22 (p=0.03) and until the end of the experiment (day 61, TGI=57%, p=0.01)." (PMID 27835884, 2016). "We demonstrated that blocking this pathway inhibits PIK3CA mutant tumour growth in vitro and in vivo, suggesting that this novel signalling pathway also plays a critical role in tumorigenesis driven by PIK3CA mutations." (PMID 27321283, 2016). "All four subjects with a single PIK3CA mutation showed weak to moderate tumor regression (−14%, −34%, −36%, and −37%)." (PMID 26989027, 2016). "Future large-scale studies investigating the correlation between EBV infection, PIK3CA mutations and tumor locations are required to address these interesting findings." (PMID 26701847, 2016). "KRAS and PIK3CA mutation frequently coexist, with activation of parallel pathways in a single tumour." (PMID 27340376, 2016). "For nine patients in the cohort, mutational analyses for KRAS, BRAF, and PIK3CA hotspots were available for matched tumor tissue, CTCs, and ctDNA." (PMID 27863403, 2016). "ESR1 mutations are present in 37% of baseline samples and are enriched in patients with luminal A and PIK3CA-mutated tumours." (PMID 27174596, 2016). "After adjusting for gender, tumor location, pathologic stage, histologic grade and adjuvant treatment, PIK3CA amplification was significantly associated with a shorter DFS (adjusted hazard ratio [AHR] 1.53; 95% CI, 1.10-2.17; P=0.02)." (PMID 27095573, 2016). "NVP-BKM120, developed with a different profile of targets within the PI3K/mTOR family, also inhibited cell proliferation in a variety of tumor cells, but preferentially inhibited tumor cells with PIK3CA oncogenic mutations." (PMID 26771642, 2016). "As a result, the PIK3CA H1047R mutation was filtered out because it was present in both the tumor and matched control." (PMID 27626691, 2016). "For PIK3CA exon 9, E542K mutations were identified in 2 tumors, Q546K mutations were identified in 2 tumors, and an E545K mutation was identified in 1 tumor." (PMID 27016421, 2016). "PIK3CA copy number gain was significantly associated with older age and larger tumor size (P=0.023 and P=0.040, respectively)." (PMID 27016421, 2016). "Confirming this in our independent unselected patient cohort, PIK3CA and PTEN loss were essentially mutually exclusive with only one tumor being both PIK3CA mutated and PTEN IHC-negative (P = 0.0116)." (PMID 27484095, 2016). "For mutational profiling, KRAS, BRAF, and PIK3CA hotspot mutations were analyzed in CTCs and ctDNA from 23 samples, nine matched liver metastases and three primary tumor samples." (PMID 27863403, 2016). "Overall, 45.2% of all tumours had a functional mutation in at least one member of the Akt signalling pathway (PIK3CA, AKT1, PIK3R1, PTEN and FOXO3)." (PMID 27161491, 2016). "BKM120 is a pan inhibitor of all four class I PI3K isoforms and inhibited tumor cells bearing PIK3CA mutations." (PMID 27623107, 2016). "This pattern suggests retention of the baseline tumour, coupled with the emergence of a second tumour containing a PIK3CA mutation (H1047R)." (PMID 27502118, 2016). "Together, these results demonstrated that the E545K mutation of PIK3CA promotes tumor progression in GBC via enhancement of the binding to EGFR." (PMID 27317099, 2016).
tumor (continued). "In this study, pooled PLR reached 42.8, meaning that patients with positive cfDNA result have more than 40 fold higher odds to have PIK3CA mutation in tumor sample compared to healthy controls." (PMID 27336598, 2016). "The overall frequency of tumor samples with NOTCH1 or PIK3CA mutations in cohort #1 or #2 was statistically higher than that of cohort #3 or #4." (PMID 26528858, 2016). "These tumor-associated PIK3CA mutations result in constitutive activation of p110α and its downstream effector AKT signaling with consequent oncogenic transformation." (PMID 26909613, 2016). "PIK3CA displayed only missense mutations (18 mutations in 17 tumours), including 11 hotspot mutations." (PMID 27406316, 2016). "Targets of these miRNAs clusters are involved in gene networks associated with tumor aggressiveness, including the ones involving PIK3CA, C-MYC and PTEN genes." (PMID 27813494, 2016). "Surprisingly, 15 out of 57 tumours harbouring PTEN inactivating mutations also had recurrent PIK3CA mutations." (PMID 27161491, 2016). "Only when the tumors were located in the middle-third of stomach, tumor with mutations of the PIK3CA gene or mutations of the PI3K/AKT pathway genes were associated with more EBV infection than those without mutations." (PMID 26701847, 2016). "The observation that PIK3CA mutations have distinct prognostic associations in ER+ tumours stratified into IntClusts is a key novel finding." (PMID 27161491, 2016). "A mutation in PIK3CA, a gene which produces a protein that increases Cox-2 and prostaglandin activity, has been shown to enhance the response of the tumour to aspirin." (PMID 27096951, 2016). "Sequencing of the ~60% of patient tumour cells with PIK3CA-E545K mutation revealed that in at least 80% of the cases, the mutation was heterozygous i.e. patient tumour cells expressed both PIK3CA-WT and PIK3CA-E545K." (PMID 27489350, 2016). "Among 18 PIK3CA mutations found in tumor, 11 were identified in the adjacent normal, but the maximum VAF was 3.52% and 6 were under 1%." (PMID 28721375, 2016). "We then tested the relation between COX-2 mRNA expression levels and both EGFR mRNA level and PIK3CA mutation status, previously determined in these tumor samples." (PMID 27835884, 2016). "Functionally, PIK3CA regulates phosphorylation of AKT1, and mutated PIK3CA has been shown to attenuate apoptotic signals and support tumor invasion." (PMID 29034103, 2016). "PIK3CA mutation frequency was higher in well/moderate differentiation tumors (12.0% vs 4.6%, P=.03), and right colon as the primary tumor site (P=.04)." (PMID 27050078, 2016). "AOA potently inhibits xenograft tumour growth of CRCs with PIK3CA mutations, despite its low potency to inhibit growth of CRC cells in culture." (PMID 27321283, 2016). "SBR grade (p=1.5.10-4), lymph node status (p=1.9.10-3), tumor size (p=1.4.10-5), ER (p=8.4.10-6) and PR (p=8.6.10-6) status as well as PIK3CA mutations (p=0.02) all had prognostic value as measured by the 5-years MFS." (PMID 27835884, 2016). "Among available DNA samples, 796 primary tumours were also evaluated for the occurrence of pathogenetic mutations in exons 9 and 20 of the PIK3CA gene (see “Methods” section)." (PMID 27737711, 2016). "The major findings reported herein are that ESR1 mutations are present in ∼40% of patients that have progressed on AI therapy and are numerically enriched in luminal A and PIK3CA-mutated tumours." (PMID 27174596, 2016). "It is reported that mutant PIK3CA contributes to tumorigenesis through increased tumor invasion, decreased apoptosis and loss of contact inhibition." (PMID 27405731, 2016). "They showed a wide spectrum of activity against many tumor cell lines in vitro including those harboring PIK3CA mutations, PTEN and LKB deletion." (PMID 27826244, 2016).
tumor (continued). "In cancer, p110α is the main isoform required for transformation by oncogenes and the encoding PIK3CA is frequently found to have suffered from one of two common activating hotspot mutations in many tumor types." (PMID 27700986, 2016). "Subsequent mutational analysis and immunohistochemical (IHC) staining with the tumor tissues just before re-treatment with everolimus revealed a PIK3CA hotspot mutation and pS6 overexpression in the primary tumor." (PMID 25886409, 2015). "Nevertheless, we tried to evaluate the utility of cfDNA as an alternative source for PIK3CA mutation analysis through comparing serum sample with matching archival tumor specimens in BTC." (PMID 26498688, 2015). "PIK3CA mutations were analyzed for correlation with several clinicopathological parameters at the time of the diagnosis: age, tumor size, tumor grade, nodal status, HR status, HER2 expression, and histological subtype." (PMID 26587011, 2015). "In one tumor a single PIK3CA E545K mutation was detected, in one tumor a single PTEN R234W mutation was detected, and in three of these tumors three different mutations were detected." (PMID 26197069, 2015). "The analysis revealed the PIK3CA mutations in both homo- and hetero-geneity in circulating tumor cells, which suggested the presence of subclones with both mutant and wild-type variant in the population." (PMID 28031920, 2015). "In a single Luminal-B-like tumor a mutation on PIK3CA gene exon 4 was also identified (2.7%), “N345K”, located in the C2 domain of PIK3CA, promoting its activity." (PMID 26540293, 2015). "PIK3CA mutation was detected In 30 (39.0%) out of 77 tumor samples available, which were balanced between HR-positive and HR-negative tumors (46.3% vs. 30.5%, p = 0.156)." (PMID 26084292, 2015). "In the AC subtype, PIK3CA mutation correlated with tumor diameter (mean diameter in PIK3CA-mutated samples 40 mm vs. 26 mm in non-PIK3CA mutated samples; P = 0.011)." (PMID 26197069, 2015). "Amongst these was an actionable hotspot mutation in PIK3CA (p.E542K), identified in plasma with an AF of 3.5% at the time of progression on trastuzumab and tamoxifen (tumour cluster 8 and plasma cluster 4)." (PMID 26530965, 2015). "In some tumor types PIK3CA mutations are frequently associated with EGFR or KRAS mutations and with a poorer prognosis." (PMID 26209091, 2015). "In our study, PTEN loss and PIK3CA E542K hotspot mutation were detected in 20% and 2% of the tumor samples, respectively." (PMID 25786580, 2015). "ER-status (positive versus negative) was distributed relatively evenly in all groups except in the MT→MT subgroup in which all but one tumor pair with PIK3CA mutations were ER-positive." (PMID 26630576, 2015). "The identification of driver PIK3CA mutations through tumour genome sequencing provided the first example of a mutated lipid kinase oncogene [5••]." (PMID 26117819, 2015). "Although the number of positive samples was limited, there was high agreement in PIK3CA mutation status between tumour gDNA and serum cfDNA." (PMID 26498688, 2015). "One salient aspect of this case was that the primary tumor was found to harbor one hotspot mutation in PIK3CA and expressed high levels of pS6 (serine 235/236 and 240/244) as well as weakly positive PTEN on IHC staining before everolimus re-treatment." (PMID 25886409, 2015). "Significance of associations between PIK3CA status and age, ER/PR status, tumor stage, and histological grade were assessed using a Fisher’s exact test, a chi-squared test, and a chi-squared test for trends." (PMID 26587011, 2015). "Higher mutant allele frequency in baseline MT tumors (n = 10; PIK3CA mutations n = 8) correlated with less tumor reduction after cycle 1 chemotherapy (R = -0.667, p = 0.035)." (PMID 26630576, 2015). "Another important point is that in the BOLERO-2 trial, PIK3CA mutational status was assessed mainly on primary tumor tissues." (PMID 25857348, 2015).
tumor (continued). "The PIK3CA missense mutation V344G was detected in Patient #1′s tumor by exome sequencing by two different laboratories." (PMID 26510912, 2015). "In our TNBC cohort, exon 9 PIK3CA activating mutations were detected in 6.7 % and exon 20 mutations in 8.3 % of tumor samples, in agreement with previously published reports on PIK3CA mutations in patients with TNBC." (PMID 26680641, 2015). "New mutations in RAS and PIK3CA emerged after therapy compared to archival tumour, and the emergence of multiple KRAS mutations in low levels after anti-EGFR therapy is a known resistance mechanism to anti-EGFR antibodies." (PMID 25889309, 2015). "Tumour samples were initially tested for presence of mutations corresponding to PIK3CA p.E542K, p.E545K, and p.H1047R." (PMID 26498688, 2015). "The analytical sensitivity of the AmpliSeq Hotspot panel was determined using serial dilutions of tumour DNA carrying PIK3CA and HRAS mutations." (PMID 25883647, 2015). "The tumor sample harbouring a PIK3CA mutation that was ER-negative was progesterone receptor (PgR)-positive." (PMID 26630576, 2015). "In the case of solid tumours, p110α-selective inhibitors have shown great promise in early-phase trials for patients with tumours bearing PIK3CA mutations." (PMID 26442967, 2015). "Four ADSQ tumors harbored mutations in the PIK3 pathway; one tumor harbored a p.C420R mutation in the C2 region and two tumors harbored a p.E545K mutation in the helical region of the PIK3CA gene, and one tumor harbored a p.Q171* mutation in the PTEN gene." (PMID 26068980, 2015). "Only four tumors (three MSS tumors and one MSI tumor, all in the training cohort) harbored PIK3CA mutation in both exons 9 and 20, which accounted for 0.5% of all studied samples and 4% of all mutated samples." (PMID 25641861, 2015). "Before re-treatment with everolimus, according to results from our previous retrospective data, we investigated the mutation of the PIK3CA gene in the tumor tissue obtained just before re-treatment of everolimus." (PMID 25886409, 2015). "Patient, tumor and treatment characteristics according to PIK3CA status and the type of PIK3CA mutations, as determined by Sanger/qPCR." (PMID 26452060, 2015). "The distribution of observed mutations was consistent with prior reports: 50% (19 of 38 patients) had a KRAS mutant tumor, 16% (6 of 38 patients) had a PIK3CA mutation, 8% (3 of 38 patients) showed a mutation in BRAF, and none showed an EGFR mutation." (PMID 25575824, 2015). "BRAF mutations were detected in 28 (23%) of the tumours and PIK3CA mutations were seen in 22 (18%) tumours mainly in exon 9 (n = 18; 82%) with 4 mutations in exon 20 (18%)." (PMID 25884297, 2015). "By using droplet digital PCR (ddPCR), we intended to evaluate the usefulness of circulating tumour DNA from serum as an alternative source for PIK3CA mutation analysis." (PMID 26498688, 2015). "PIK3CA mutations were found in 0–27% of GBM tumor samples, depending on the study and the detection method used." (PMID 24718026, 2014). "PIK3CA mutation analysis was then performed on the 242 EpCAM-captured single tumor cells (185 CTCs, 24 DTCs, and 33 tumor cells)." (PMID 24947048, 2014). "The prognosis of patients with PIK3CA mutations who have been treated with endocrine therapy is determined by both tumor biology and treatment effect, where the latter can range from substantial to no treatment effect." (PMID 24467828, 2014). "With regard to the tumor response, a few studies have shown the predictive meaning of PIK3CA mutation." (PMID 25542038, 2014). "While most of the single nucleotide variations were not shared between patients, gain of chromosome 1q and activating mutations in PIK3CA were observed recurrently in some of the early neoplasia samples." (PMID 24887547, 2014). "Three additional private events were observed in PIK3CA including two E545K mutations specific to the primary tumor and one in-frame deletion at N107 specific to the metastasis." (PMID 25164765, 2014).
tumor (continued). "In only 1 out of 6 patients, CTCs shared the mutational state of the oncogenes ERBB2 and PIK3CA with the primary tumor." (PMID 25358515, 2014). "In fact, the Detroit 562 cell line was relatively resistant to PI3K pathway inhibitors despite harboring a PIK3CA mutation suggesting that additional factors contribute to the sensitivity of tumor cells to this class of agents." (PMID 24599075, 2014). "In this study, all six SDC patients showed upregulated expressions of PIK3CA protein in tumor lesions, but only two of them harbored PIK3CA genetic mutations." (PMID 24511546, 2014). "Here we analyze a series of single tumor cells, CTCs, and DTCs for PIK3CA mutations and report CTC and corresponding metastatic genotypes." (PMID 24947048, 2014). "Two of this tumor's mutations with much larger signal in RNA than DNA occurred in PIK3CA (p.H1047R) and GATA3 (p.S412fs)." (PMID 24970867, 2014). "DNA extracted from 30 tumor samples was analyzed by Sanger sequencing for common PIK3CA mutations; 10 samples were found to carry PIK3CA mutations." (PMID 25222559, 2014). "Potent activity against AKT kinases and relative selectivity against a large kinase panel translates in cells as increased sensitivity of tumor cell lines with PIK3CA and/or PTEN mutations, genes known to regulate AKT pathway activation." (PMID 24978597, 2014). "Additional tumor cell clusters from two FFPE samples of primary tumor and a lung metastasis were also analyzed for PIK3CA mutations." (PMID 24947048, 2014). "The 1047H>H/R missense mutation is the most common mutation reported in tumor samples and accounts for 24.4% of all variations of the PIK3CA coding sequence submitted to the COSMIC database." (PMID 24932282, 2014). "Other possible explanations include pAKT modulation by tumor/stromal interactions, cell lineage specificity, or the association of pAKT with other mutations such as PIK3CA regulatory domain mutations as they have also been shown to alter pAKT." (PMID 24559118, 2014). "Among 10 of the patients with mutation-positive pre-surgery tumor cfDNA, analysis of post-surgery plasma detected PIK3CA mutations in five." (PMID 25222559, 2014). "NGS performed on a tumor sample from the chest wall biopsy obtained at the time of diagnosis revealed PIK3CA mutation H1047R, CTNNB1 mutation S37C, and protein tyrosine phosphatase delta (PTPRD) mutation S1845fs*2." (PMID 24931142, 2014). "In two cases, a subpopulation of tumor cells with a mutation in exon 9 of PIK3CA was detected only in the metastasis." (PMID 24156022, 2013). "The association between tumor mucinous differentiation and PIK3CA mutation has been previously reported." (PMID 23785428, 2013). "PIK3CA mutations were detected in 37 tumours (16.4%), 20 in exon 9 (8.8%) and only five in exon 20 (2.2%)." (PMID 23374602, 2013). "We assessed mutations in the three hotspots of the PIK3CA gene (E542K, E545K and H1047R) in both tumor groups." (PMID 23663520, 2013). "In another study it was identified that in HNPCC, mutation in PIK3CA was identified in 14% tumor while over expression in 59% of tumor." (PMID 23768168, 2013). "Cancer gene mutation screening using a combination of multiplexed PCR and mass spectroscopy revealed a PIK3CA exon 20 H1047R mutation in the primary tumor, lung metastasis, and liver metastasis." (PMID 23766666, 2013). "The adverse prognostic effect of PIK3CA mutation on survival was restricted to patients with a wild-type BRAF mutated tumor." (PMID 23785428, 2013). "The association between PIK3CA mutations and poor prognosis was particularly marked in patients with hormone receptor positive tumours." (PMID 23441137, 2013). "The study has also revealed differences of MBC to FBC and between sporadic and familial MBC which are of importance in optimising treatment strategies and underlying relevance of the PIK3CA/mTOR pathway in tumour biology." (PMID 23971979, 2013).